SERPINB2 (serpin family B member 2)
Diseases named in the same sentence as SERPINB2 in open-access papers (continued):
Sharing a sentence is not in itself a finding about the gene and the disease.
tumor (continued). "In summary, although clear links between tumor SerpinB2 expression and cancer prognosis have been established, the cells and mechanism(s) involved remain poorly understood." (PMID 24644264, 2014). "A key observation made herein is that tumor-expressed SerpinB2 is present on the surface of tumor-derived MPs." (PMID 24644264, 2014). "qRT-PCR analysis of the tumors in this latter experiment illustrated that SerpinB2 expression in B16-SerpinB2 cells was retained in vivo over the 12–15 days of tumor growth." (PMID 24644264, 2014). "Previous in vitro work suggested a role for tumor cell-expressed SerpinB2 in suppressing tumor cell growth 6,10,11,25." (PMID 24644264, 2014). "Herein we observed uPA on tumor-derived MPs as well as reduced migration and invasion and metastasis for SerpinB2-expressing tumor cells." (PMID 24644264, 2014). "Herein, we provide evidence that at least one of the activities of SerpinB2 on cancer-derived MPs is to suppress uPA-mediated tumor cell migration, invasion, and metastasis." (PMID 24644264, 2014). "We also observed that SerpinB2-expressing tumor cells showed reduced migration and length of invadopodia-like structures, an activity likely mediated by inhibition of uPA 13–15,27." (PMID 24644264, 2014). "The upregulation of the serine protease inhibitor and matrix metalloproteinase genes Serpinb2 and Mmp10 in the tumor microenvironment of knockout mice suggests a tumor-suppressive function through the regulation of extracellular matrix remodeling and modulation of immune responses 58,59." (PMID 41377951, 2025). "Furthermore, our data shed new light regarding the regulation of SERPINB2 and support its tumor-suppressive action in TNBC." (PMID 38741146, 2024). "The reports revealed that SerpinB2 expression in tumor cells may function as a survival factor by repressing proapoptotic signal transduction." (PMID 38956496, 2024). "Several mechanisms have been proposed where SerpinB2 expression by tumor cells might influence tumorigenesis and include the inhibition of apoptosis or uPA signaling." (PMID 38956496, 2024). "The inhibitory effect of Id1 knockout in TAMs on CSC marker expression, tumor sphere formation ability, and tumor invasiveness could be reversed by depletion of Serpinb2 (Serpinb2KD)." (PMID 37996458, 2023). "The reason for the differing role of SERPINB2 between these two tumour models is unclear." (PMID 35418690, 2022). "However, the role of SerpinB2 as a prognosis marker in tumor progression or suppression remains controversial." (PMID 28427146, 2017). "Representative tumor sections were stained for SerpinB2, Neuroserpin, and L1CAM." (PMID 29207598, 2017). "Although others have explored the prognostic value of SerpinB2 in BC patients, the status of SerpinB2 from tumor extracts was evaluated using RT-PCR and immunoenzymatic assays, which do not discriminate between cancer and stromal cells that also express SerpinB2." (PMID 28427146, 2017). "However, to our knowledge our study was the first to investigate relationships between miR-200c, miR-141, and SerpinB2 in BC tumor tissues." (PMID 28427146, 2017). "This discrepancy may reflect the use in previous studies of transfection and clonal selection to generate SerpinB2-expressing tumor cell lines." (PMID 24644264, 2014). "In tumor settings, SerpinB2 expression in host tissues may have little influence or may simply be too low to mediate significant effects." (PMID 24644264, 2014). "Previous studies reported that SerpinB2 expression by tumor cells reduces metastases 13,15." (PMID 24644264, 2014). "In these studies it is often unclear whether the SerpinB2 is expressed by the transformed cells or by tumor-infiltrating host cells, although it is clear that tumor cells can express SerpinB2 6,8." (PMID 24644264, 2014). "In addition, silencing Serpinb2 in TAMs enhanced the tumor invasiveness and tumor sphere-forming ability, which could be reversed by Y15 treatment." (PMID 37996458, 2023).
tumor (continued). "However, IHC analysis can reveal specific SerpinB2 locations in tumor tissues." (PMID 28427146, 2017). "Our study has demonstrated that C/EBP-β plays an important role in mediating both constitutive and LPS-induced transcription of the SerpinB2 gene, which may have implications for the inflammatory phenotype of infiltrating immune cells in the tumor microenvironment." (PMID 23472114, 2013). "provided spatially resolved mechanistic and functional evidence that tumor cell expression of SERPINE1 (PAI-1) and SERPINB2 (PAI-2) in PDAC generates a fibrin(ogen)-rich ECM." (PMID 41601623, 2026). "The cluster 6 monocytes were defined by high expression of multiple pro-tumor genes (IL1B, SERPINB2, CCL2, CXCL1, CXCL5, CXCL8, CCL3, CCL20)." (PMID 40176808, 2025). "We, therefore, confirmed the ALDH1A3‐dependent regulation of PLAT, PLAU, and SERPINB2 by RT‐qPCR and visualized the co‐expression correlation of the genes with ALDH1A3 in the patient tumour data." (PMID 37753740, 2024). "Our study revealed that the TME endowed TAMs with high ID1 expression, which interacts with STAT1 to inhibit CCL4 and SerpinB2 transcription, two STAT1 target genes, leading to CD8+ T cell exclusion in tumor sites and cancer stemness traits maintenance." (PMID 37996458, 2023). "Three genes, SERPINB2, TAGLN, and HIST1H2BD, showed high expression and significant differences between normal and tumor tissue in this analysis." (PMID 36982651, 2023). "The evidence suggested that ID1 inhibits the transcription of SerpinB2 and CCL4 in macrophages to promote tumor immune evasion and augment the tumor-initiating capacity of CRC cells, ultimately resulting in aggravated tumor growth and metastasis." (PMID 37996458, 2023). "SERPINB2, also known as plasminogen activator inhibitor type 2 (PAI-2), has been shown to be directly related to tumor promotion and poor prognosis in various cancers such as bladder, colorectal, endometrial and ovarian cancers." (PMID 30965654, 2019). "Conversely, by gene array studies, a decreased expression was shown after CPT1A silencing of several factors, such as SERPINB2 and PDGF-A, related to cell survival and tumor progression." (PMID 26799588, 2016). "Upregulation of anti-apoptotic genes, including BAG1, BCL11B and SERPINB2, and downregulation of apoptotic genes, such as DAPK2, HRK and TP53INP1, can promote tumor cell survival." (PMID 23024765, 2012). "In contrast, SERPINB2 was not negatively co‐expressed in all patient tumour and normal adjacent samples as expected." (PMID 37753740, 2024). "We previously found that SerpinB2-upregulated MDA-MB-231 cells that were stably overexpressing miR200c promoted lung metastasis and boosted macrophage infiltration in tumor tissues, but the knockdown of SerpinB2 decreased lung metastasis and macrophage infiltration in xenograft mouse models." (PMID 38956496, 2024). "SerpinB2 or plasminogen activator inhibitor-2 (PAI-2) is an inhibitor of extracellular urokinase plasminogen activator (uPA) and is expressed in a number of cell types, especially tumor cells and immune cells." (PMID 35768767, 2022). "SERPINB2, whose complex functions and regulations are not yet fully understood, are induced by multiple inflammatory molecules and anti-tumor agents." (PMID 36497110, 2022). "With the regulation of the tumor microenvironment, more genes were upregulated with over two-fold differences in both HK1 and C17 xenografts after CYLD knockout, including BCL2A1, CXCL1, BIRC3, SERPINB2, total VEGF, TNFA, and VEGFA." (PMID 32708712, 2020). "Traditionally, SERPINB2, a secreted glycoprotein that inhibits tPA and urokinase, has been described as a tumor suppressor that inhibits tumor growth and metastasis, whereas SERPINB1 promotes tumor progression." (PMID 29404274, 2017). "They evaluated SerpinB2 levels from primary tumor lysates using immunoenzymatic assays, which do not reflect the expression site of SerpinB2 in tumor cells." (PMID 28427146, 2017).
tumor (continued). "The previously reported role for SerpinB2 in modulating Th1/Th2 markers after infection or vaccination 12,23,24, thus does not appear to extend to tumor settings." (PMID 24644264, 2014). "Taken together these experiments suggest that SerpinB2 expression by transformed cells does not significantly affect tumor growth in vivo or cancer cell proliferation in vitro." (PMID 24644264, 2014). "In conclusion, although we have not explored all possible tumor types and/or settings, our data does not support the view that SerpinB2 expression by cancer cells affects their growth directly." (PMID 24644264, 2014). "In our study, tumor cells overexpressing SerpinB2 did not display SerpinE1 or uPA downregulation." (PMID 28427146, 2017). "SerpinB2 expression levels in these transduced tumor cell lines were thus not supraphysiological." (PMID 24644264, 2014).
cancer (88 papers, 1991 to 2026). A tumor composed of atypical neoplastic, often pleomorphic cells that invade other tissues. "A low-expression profile of SERPINB2 is linked with poor prognosis in various cancers, including STAD." (PMID 36241983, 2022). "SerpinB2 is expressed by a variety of cells and is implicated in various diseases including cancer, inflammation, and immune-associated diseases." (PMID 35768767, 2022). "Taken together, it is conceivable that the identified SERPINB2 mutation in cancer-associated PSCs results in enhanced pro-tumorigenic activity of PSCs." (PMID 35941161, 2022). "SERPINB2 encodes a serine protease inhibitor also known as PAI-2 (plasminogen activator inhibitor type-2) and has a context-dependent role in human cancers." (PMID 34116687, 2021). "SERPINB2 overexpression has been linked with inhibition of invasion and cell migration, and prolonged survival in different cancers." (PMID 33324695, 2020). "RNA-Seq analyses determined that loss of Kindlin-2 expression in BC cell lines resulted in a significant increase in SerpinB2 and p21 expression, both known to be associated with cancer cell senescence." (PMID 31308359, 2019). "TM4SF1 and SerpinB2 were previously implicated in cancer development particularly in cancer stem cell biology." (PMID 29290987, 2017). "Further experiments suppressing or elevating SerpinB2 expression provided additional evidence that SerpinB2 levels are associated with the invasive characteristics observed in cancer cells." (PMID 27558531, 2016). "Expression of SerpinB2 (plasminogen activator inhibitor type 2/PAI-2) by certain cancers is associated with a favorable prognosis." (PMID 24644264, 2014). "SerpinB2 expression has been associated with both inflammation and cancer, and is a favorable or unfavorable prognostic indicator depending on cancer type." (PMID 23472114, 2013). "Finally, currently there is poor evidence to support the role of SERPINB2 in BC development but its enhanced expression has been linked with metastatic progression in various cancer types." (PMID 35158756, 2022). "Loss of SERPINB2 leads to a faster migration rate and less expression of Caspase-3 in cancer cells." (PMID 36497110, 2022). "Three previously identified pro-thrombotic genes (F3, SERPINE1, and SERPINB2) were analyzed and, for pan-cancer comparisons, gene expression was Z-standardized and summarized as a composite coagulome score." (PMID 41976278, 2026). "Compensatory mechanisms involving SerpinE1 and SerpinB2 have implications in various diseases, including cancer." (PMID 38956496, 2024). "CPT1AV2 knockdown upregulates the levels of HDAC1 and alters the expression of multiple cancer-related genes, including the downregulation of SERPINB2." (PMID 37884951, 2023). "The role of SerpinB2 expression by diverse types of cells in cancer growth and metastasis is controversial." (PMID 35768767, 2022). "SERPINB2 expression significantly increased in response to various tumorigenic agents in multiple cancer stem cell types." (PMID 36497110, 2022). "The roles of SERPINB2 are contentious and seemingly contradictory under different circumstances, as cancer-promoting and -suppressing functions were reported, even within the same cancer type." (PMID 36497110, 2022). "On the other hand, high levels of serpin B2 (SERPINB2) have been demonstrated in the cancer cells of vessel co-opting brain metastatic lesions, which play a key role in apoptosis suppression." (PMID 35267627, 2022). "This phenomenon was likely due to the short half-life of SERPINB2 protein and clearance or expulsion by cancer cells." (PMID 36497110, 2022).
cancer (continued). "In brain metastasis, overexpression and secretion by cancer cells of a molecule called SerpinB2 has been reported to play a key role in tumor escape from brain defenses." (PMID 34502091, 2021). "This indicates that, besides zinc content, an additional transformative process must undergo in MDA-MB-231 parental cells during cancer progression to express sufficient SerpinB2 in order to escape from niche’s defenses against cancer cells’ invasion." (PMID 34502091, 2021). "Intriguingly, TFPI2 shares a common protease target, plasmin activity, with SerpinB2, and the latter promotes the survival of brain vascular coopting cancer cells." (PMID 34249699, 2021). "SerpinB2 is an inhibitor of the urokinase plasminogen activator, which promotes cancer cell survival by blocking the niche defenses." (PMID 34502091, 2021). "SerpinB2 expression in cancer cells has been shown to reduced migration and metastasis and to reduce the length of migration-associated invadopodia-like structures." (PMID 31455834, 2019). "Multiple types of cancer cells transfected with shRNA targeting SERPINB2 were seeded at 1, 10, 100 and 1000 cells/well." (PMID 30965654, 2019). "The expression levels of SERPINB2 were markedly enhanced with the initiation and progression of breast, colorectal and liver cancers." (PMID 30965654, 2019). "The Gene Expression Omnibus (GEO) database was analyzed to verify the increased SERPINB2 expression with the initiation and progression of multiple cancer types." (PMID 30965654, 2019). "Given the CEMiTool results and the reported role of SerpinB2 in suppressing cancer cell metastasis, the migration of RPM from SerpinB2−/− and SerpinB2+/+ mice was compared using the standard IncuCyteTM scratch wound cell migration assays." (PMID 31455834, 2019). "For example, SerpinB2 has been reported (i) to modulate Th1/Th2 immunity, (ii) to inhibit apoptosis in certain settings, (iii) to inhibit cancer metastasis and migration, (iv) to regulate differentiation and proliferation and (v) to inhibit IL-1β processing." (PMID 31455834, 2019). "Macrophage SerpinB2 thus appears to have a similar function to SerpinB2 expression in cancer cells, where in a range of settings SerpinB2 expression has been shown to inhibit metastasis/invasion." (PMID 31455834, 2019). "To investigate the relationship between poor prognosis and increased SERPINB2 levels, we analyzed the available clinical datasets for various cancer types using the Oncomine data repository." (PMID 30965654, 2019). "It is especially interesting as the precise role of SERPINB2 remains an enigma and its connection to cancer has been reported." (PMID 27796684, 2017). "SerpinB2 is upregulated during inflammation, and is expressed in diverse cell types, including cancer cells, macrophages, and fibroblasts." (PMID 28427146, 2017). "SerpinB2 inhibition of uPA in tumors is of significant interest in prognosis and clinical outcome prediction in various cancers." (PMID 28427146, 2017). "SerpinB2 belongs to a superfamily of serpins which act as protease inhibitors (Serine Protease Inhibitors) and has diverse roles in cancer development and metastasis." (PMID 29207598, 2017). "The expression of SerpinB2 is highly related to its target, uPA, in the prognosis of cancer patients." (PMID 27558531, 2016). "Effects on cell cycle in vitro were also not observed when transient transfection was used to express SerpinB2 in cancer cell lines." (PMID 24644264, 2014). "Cancer cells have been shown to express SerpinB2 6,8 and several studies have suggested that SerpinB2 expression by cancer cells can inhibit their proliferation in vitro 6,10,11,25." (PMID 24644264, 2014).